IL4 (interleukin 4)
Diseases named in the same sentence as IL4 in open-access papers (continued):
Sharing a sentence is not in itself a finding about the gene and the disease.
infection (continued). "Both the immunization and muscular phase + immunization groups had higher concentrations of serum IL-4 than the control, and the infection increased IL-4 and IL-10 levels related to the immunization group." (PMID 39066367, 2024). "Following topical application of IONPs, there was an increase in IFN-γ secretion and a decrease in IL-4 levels in the lesions of infected mice, indicating the induction of a Th1 response that effectively controls the infection." (PMID 39211053, 2024). "This aligns with a report by Steenhard and colleagues showing an increase in parasite-specific IL-4 secretion from circulating cells following 3 weeks of trickle infection." (PMID 38799456, 2024). "We next investigated eosinophil recruitment and IL-4 secretion in the spleen post infection in vivo." (PMID 38413575, 2024). "Regarding IL-4; with treatment with Linex, Albendazole, or combined therapy; the levels decreased in compared to infection control group." (PMID 39609767, 2024). "Eosinophil-derived IL-4 has been identified as a driver of macrophage activation in mice following infection with the nematode Strongyloides venezuelensis or the protozoan Leishmania major." (PMID 39083533, 2024). "The goblet cell response that follows infection with H. diminuta was delayed in Pou2f3-/- mice, possibly as a consequence of reduced or delayed IL-4/IL-13 signaling downstream of tuft cell activation." (PMID 39083533, 2024). "In general, the Il-4 and Il-13 gene expression profiles of co-infected animals were more similar to Hb than Tg infected animals at day 5 post Tg infection." (PMID 38950025, 2024). "The variability in the literature concerning IFN-γ underscores the significance of our study, which assessed IFN-γ at multiple infection stages and examined the dynamic release patterns of IL-4, IL-1β, and IL-6." (PMID 39408907, 2024). "Regarding cytokine levels, all groups treated with M. fragrans had low levels of IFN-γ and IL4 on day 21 post-infection." (PMID 39507782, 2024). "To test this, we incubated BMMs, given these are a major source of macrophages to replenish peritoneal cavity in response to infection, in the presence of TcES ± recombinant IL-4 for 48 h." (PMID 38842647, 2024). "On day 6 of infection, the study found elevated IL-4, IL-5, IL-13, and IL-10 levels in infected mice." (PMID 38166140, 2024). "It has been shown that eosinophils are a critical source of IL-4 during the early events after infection, inducing the survival of tissue-resident macrophages that act as a replicative host for L. major." (PMID 38198296, 2024). "In comparison to L. major, L. braziliensis induces significantly lower expression of IL-4, IL-10, and IL-13 in the early phase of infection in BALB/c mice." (PMID 38543944, 2024). "At days 4, 6, 8, and 10 PI, visually distinct patterns between infection parameters from baso IL-4/IL-13 (−) mice and baso IL-4/IL-13 (+) mice provided ample significant correlations and fold differences for network analyses." (PMID 38780542, 2024). "On the other hand, Leishmania is capable of directing the response to the Th2 profile, characterized by the production of IL-10 and IL-4 cytokines, which inhibit macrophages and lead to proliferation and resistance to infection." (PMID 38312642, 2024). "Meantime, IL4 also has a great advantage against infection, as it can enhance the production of INF-γ to reduce the tissue cysts caused by T. gondii." (PMID 39416787, 2024). "Patients in the death group presented higher levels of IL-4 and IL-1β at all timepoints evaluated, maintaining constant elevated levels throughout the course of infection." (PMID 39408907, 2024). "During the time course of infection, the Th1 immune response alters to a Th2 response, with increased levels of IL-4, IL-5, and IL-13." (PMID 39329761, 2024).
infection (continued). "At 72 h post‐infection, these cytokine/chemokine levels shifted with significantly lower IFNγ and IL‐4, significantly higher IL‐5, IL‐10, IL‐17a, and CCL‐5/RANTES, and comparable IL‐2 and TNFα levels." (PMID 37990641, 2024). "In conclusion, from a single infection, the streptococci and CNS quarter showed varied immune responses, including trendily higher IL-6 and IL-4." (PMID 39195804, 2024). "The transcription levels observed at the late stage of infection were similar for IL4, IL10 and IL12 but there were significantly increases for YM1 from day 15 to day 30 DPI." (PMID 38511816, 2024). "As the infection progresses, a delicate shift occurs, characterized by a transition to adaptive immunity, guided by cytokines like interleukin-4 (IL-4), interleukin-5 (IL-5), and interleukin-13 (IL-13), promoting antibody production and T-cell responses." (PMID 38694310, 2024). "Immunohistochemistry revealed altered levels of IL20, IL17A, IL4, and psoriasin, which are involved in infection." (PMID 39337422, 2024). "IL-4 enhances IFN-γ production in the late infection stage, while IL-10 inhibits inflammation and prevents CD4+ T cell-mediated severe immunopathology." (PMID 39597646, 2024). "Both the immunization and enteric phase + immunization groups had higher concentrations of serum IL-4 and IL-10 than the control, and the infection increased IL-4 and IL-10 levels related to the immunization group." (PMID 39066367, 2024). "To assess the link between tuft cell infection and viral diversity, we treated WT and Ifnlr1-/- mice with two doses of recombinant IL-4." (PMID 38701091, 2024). "During chronic Schistosoma mansoni infection, IL-4-producing Th2 cells rapidly increase and reach a plateau level maintaining their proliferative ability at 8 weeks post-infection." (PMID 38788198, 2024). "As a surrogate of host response to infection with H. diminuta, infected mice showed increased concanavalin-A (con-A) stimulated splenic production of IL-4, IL-10, and IL-13, the variability in the data reflecting the individual mouse’s response to the worm." (PMID 39083533, 2024). "Our results showed increased in IFN-γ levels and decreased IL-4 and IL-13 with treatment with Linex, Albendazole or both during the muscular phase of infection." (PMID 39609767, 2024). "Collectively, these data suggest that basophil-derived IL-4 and IL-13 control the activation and proliferation of MCs after P. y. yoelii 17XNL infection." (PMID 38780542, 2024). "Worm antigen and mitogen evoked production of IL-4 and IL-10 by splenocytes from wild-type and Pou2f3-/- mice was not appreciably different, suggesting similar systemic immune reactivity to infection with H. diminuta." (PMID 39083533, 2024). "Intestinal infection characteristically induces T-helper- 1 cell (Th1) cytokines early in infection followed by a gradual increase cytokines released by T-helper 2 cells such as IL-4 and IL-13, which play a crucial roles in the expulsion of the worms." (PMID 39609767, 2024). "In contrast, the cytokines IL-4 and IL-10 of the Th2 cells play a role in the advancement of the infection." (PMID 38667922, 2024). "Mast cells, basophils, dendritic cells, neutrophils, monocytes, and macrophages have prominent roles whereby IL-4/IL-13 polarizing cytokines participate in resolving the infection in favor of the host." (PMID 38392907, 2024). "We also evaluated the changes in the concentration of cytokines produced by T cells at this time point post-infection: IL-4, TNF-α, and IFN-γ in BAL and serum." (PMID 38675794, 2024). "infection induces eosinophils to secrete IL-4 to inhibit the JNK/caspase-3-dependent apoptosis of CD8+ T cells at early stage, which consequently promotes generation of immune memory and protective immunity against infection." (PMID 38413575, 2024). "In symptomatic infection, the roles of IL-4 and IL-10 advance, reducing the effects of Th1 cytokines." (PMID 38399674, 2024).
infection (continued). "Infection with helminths induces polarized type 2 immunity characterized by elevated expression of cytokines, including IL-4, IL-5, IL-10, and IL-13." (PMID 38166140, 2024). "By monitoring IL-4 levels, clinicians can gain valuable information about the nature and progression of the infection, aiding in diagnosis and treatment decisions." (PMID 38251210, 2024). "As for IL-18, in L. major–infected BALB/c mice, this cytokine was shown to upregulate IL-4 production, favoring the persistence of infection." (PMID 38707903, 2024). "T helper 2 cells can produce cytokines, including IL-4, IL-5, IL-10, and IL-3,27 and the response of these cells plays a central role in protection against infection." (PMID 39807418, 2024). "Upon infection, IL-4+ cells decreased precipitously, giving rise to increased levels of the Th1 inflammatory cytokines TNF-α and IFN-γ." (PMID 38814732, 2024). "The expression of GM-CSF, IL-4, IL-5, IL-10, IL-13, KC, and VEGF in Th2 cells, and IL-2, IL-4, IL-5, IL-10, and IL-17 in NK cells significantly increased after infection (PBS-treated group)." (PMID 39264964, 2024). "The frequency of CD4+IFN-γ+ T cells, CD8+IFN-γ+ T cells, and CD4+IL-4+ T cells in the dLNs and at the site of infection of Gsdmd-/- and C57BL/6 control mice remained unchanged, as determined by flow cytometry." (PMID 39250503, 2024). "On the other hand, Swiss mice presented higher IL-4 mRNA expression in the hepatic tissue, in addition to higher hepatic granuloma size, at seven weeks after infection." (PMID 38896633, 2024). "We administered IL-4 to mice prior to infection, a treatment well-established to enhance intestinal tuft cell numbers, and found that this enhanced infection and barcode richness in WT and Ifnlr1-/- mice." (PMID 38701091, 2024). "A. flavus brain infection in mice showed elevated secretion of IFN-γ, IL-12p40, and IL-6, while simultaneously showing decreases in the secretion of the Th2 cytokine IL-4 and the Th17-boosting cytokine IL-23 during the later stage of infection." (PMID 38667922, 2024). "To then gain insights into germinal center cytokine effects on EBV-infected primary B-cells, we treated cells at 7 days post-infection with vehicle control, IL-4, IL-15, IL-21, IL-27 or multiple combinations thereof." (PMID 38683861, 2024). "Together, our findings demonstrated that eosinophils produce IL-4 to inhibit JNK/Caspase-3 dependent apoptosis of CD8+ T cells induced by infection." (PMID 38413575, 2024). "Chronic mastitis, which is characterized by persistent inflammation of the mammary gland, frequently results in higher IL-4 levels as part of the immune system’s attempt to fight the infection, which is directly increased in SCC." (PMID 39195804, 2024). "Infection with the hookworm N. brasiliensis induces a strong Th2 response characterized by high levels of IL-4." (PMID 36753434, 2023). "Intriguingly, after 30 days of infection, the levels of all cytokines decreased significantly over time, yet anti-inflammatory cytokines (IL-4, IL-5, IL-10 and IL-13) decreased to a lesser extent." (PMID 37691941, 2023). "Compared to this, pre-stimulation with IL-4 leading to an anti-inflammatory (M2) phenotype prior to infection increased intracellular bacterial numbers." (PMID 37190073, 2023). "Glycan products produced by F. hepatica have also been reported to induce modulation of DC maturation, resulting in increased production of IL-10 and IL-4 during infection, inducing a Th2/regulatory-polarized immune response." (PMID 38149297, 2023). "GATA-3 mRNA expression is observed in the spleens of dogs in the first month following experimental infection with L. infantum, with detection of Th2-type cytokine mRNA (i.e., IL-4)." (PMID 36719867, 2023). "IL-12 promotes IFN-γ production and T cell proliferation, while IL-4 promotes IFN-γ production late in infection." (PMID 37025641, 2023).
infection (continued). "T lymphocyte helper 1 (TH-1), produced secondary to infection, downregulates TH-2 production; Th-2 by secreting interleukin 4 (IL-4) downregulates Th-1 activity; and T lymphocyte regulators (T-regs) suppress both Th-1 and Th-2." (PMID 37842462, 2023). "Lung CD4+ T cells displayed significantly increased Th1 (IFNγ) and Th2 (IL-4, IL-5, IL-13) cytokine production potential during pre-patent infection at the higher dose." (PMID 37012228, 2023). "Further, lung CD4+ T cells had significantly increased Th1 (IFNγ) and Th2 (IL-4, IL-5, IL-13) cytokine production potential during patent schistosome infection, at a greater magnitude than observed in pre-patent infection." (PMID 37012228, 2023). "We next probed the effect of chronic RSM treatment in a vaccination model for Hp involving secondary infection, where IL-4-polarized macrophages are critical for protection." (PMID 37747879, 2023). "Meanwhile, Th2 cells mainly respond to the infection of extracellular bacteria, fungi, and parasites, by secreting IL-4, IL-6, and IL-10." (PMID 37357919, 2023). "IL-4 has is also important in the late stages of infection, in which it can promote IFN-γ production." (PMID 37122740, 2023). "The results showed an increase in IL-4 mRNA levels both upon infection and transfection as compared to their respective vector controls." (PMID 37928551, 2023). "Conversely, a humoral immune response characterized by the production of anti-inflammatory cytokines, such as IL-10 in VL or IL-4 in CL, by CD4+ T helper cells (Th2) leads to susceptibility to infection." (PMID 37569710, 2023). "For instance, genetic variants in IL13, IL4, IL10, IFNG and STAT6 genes were associated not only with infection intensities and re-infection of S. mansoni after treatment, but also with S. haematobium infections and its infection intensities." (PMID 36889485, 2023). "Further, inhibition of DKK1 in vivo or platelet depletion resulted in reduction in IL-4, IL-10 and L. major parasite burden as well as cellular recruitment to the draining lymph node and site of infection." (PMID 37885890, 2023). "Conversely, IL-4 and IL-10 transcriptional levels were reduced in the livers of the mice treated with anti-PD-L2 during the late stage of infection (9–12 weeks post-infection)." (PMID 36668953, 2023). "Results of that study suggested that the increased IL-4 serum levels in farm pigs were probably indicative of a derailed immune response observed after infection." (PMID 36680273, 2023). "Surprisingly, we found that IL-4, IL-5, IL-6, IL-10, and IL-13 levels reached peaks after 30 days of infection and then decreased in a time-dependent manner." (PMID 37691941, 2023). "The levels of Th2 cytokine (IL-4) remained low in the lungs of anti-Gr1-treated mice at 8 weeks after infection." (PMID 36776848, 2023). "Concurrent infection with N. brasiliensis or with Schistosoma mansoni promoted T cell-derived IL-4 production and suppressed Th1/Th17 differentiation in the spleen." (PMID 36753434, 2023). "In late-phase infection, the elevated IL-4 and IL-13 activate the alternative macrophage pathway (M2), which can produce molecules that are toxic to the fluke and contribute to fibrosis and tissue repair." (PMID 37152685, 2023). "The TRMs from the eoCre: Il4/13f/f mice displayed significantly lower expression of Mrc1, Ccl24, and Tslp than WT mice after infection, whereas Il4r expression remained unchanged." (PMID 38030609, 2023). "Research has shown that IL-4 expression is downregulated after HTC macrophage cell line infection with H9N2, which plays a key role in regulating Th2-type immune responses." (PMID 37357919, 2023). "CD4+ T cells play a pivotal role in infection, inflammation, and autoimmunity through cytokine release, including IL-4, IL-13, and IL-17, which induces a cascade of reactions that act against allergens." (PMID 36980282, 2023).
infection (continued). "This is the case in which IL-4 produced by mast cells and other innate cells at the initial infection site leads to the induction of responses characterized as anti-inflammatory Th2 polarization." (PMID 37235324, 2023). "Accordingly, mRNA‐expression levels of anti‐inflammatory cytokines (IL‐4 and IL‐13) were increased in Bsep−/− mice upon infection." (PMID 37641872, 2023). "As infection progresses, an IL-4 increase can be further observed on SWAP-stimulated spleen and liver cells from 4-week-old infected mice." (PMID 38133315, 2023). "In contrast, levels of Th2 type cytokines (IL-4 and IL-13) in Tigit-/- mice were lower than those in WT mice at 4 weeks post infection." (PMID 36930687, 2023). "Our previous studies infected with MHV68 intraperitoneally and found reactivation specifically in peritoneal macrophages following HP infection or intraperitoneal IL-4 treatment; therefore, we maintained the dose and route of infection." (PMID 37847677, 2023). "Cytokine assay confirmed that as the infection time prolonged, the levels of inflammatory cytokines (especially IL-6 and: IL-1β) decreased, while anti-inflammatory cytokines (especially IL-4) increased." (PMID 38076459, 2023). "In the experiments against N. brasiliensis, it has been shown that, after 5 days of infection, the IL-25 activated iILC2s to highly express IL-13, IL-5 and IL-4, and only the iILC2s expressed the Th2 cytokines." (PMID 37173731, 2023). "An opposite tendency was observed in the secretion of IL-4, which was increased in MIF-deficient mice after infection compared to WT mice." (PMID 38275363, 2023). "When neutrophils before infection were preincubated with pGSN, a significant decrease in IL-4, IL-6, and TNF-α secretion was observed." (PMID 36802172, 2023). "To validate these observations in vivo, we monitored IL-4 expression at mRNA level in THP-1 macrophages both upon infection with M.smeg::MtbEspR, and transfection with pC-EspR by qRT-PCR." (PMID 37928551, 2023). "IL-4, IL-6, and IL-1 beta peaked by day 9 post-infection then dropped immediately prior to severe disease onset." (PMID 36992478, 2023). "Of interest, IL-4 priming in these pre-stimulation conditions resulted in higher bacterial numbers at 30 min after infection as compared to unpolarised macrophages (Ctrl), reflecting higher bacterial uptake." (PMID 37190073, 2023). "Our data shows that, as compared to ancestral Wuhan-Hu-1 strain, BA.5 infection in hACE2.Tg mice shows an overall decrease in the mRNA expression of IL-4, IL-6, IL-17A, and IL-33." (PMID 37704701, 2023). "The opposite trend was true for IL-2 and IL-4 with detected increased expression as infection progressed from 2 to 7 dpi." (PMID 37507719, 2023). "Among the mentioned cytokines, the expression level of IL-4 compared to IL-10 was significantly higher at the end of the infection period than at the beginning (P<0.0001)." (PMID 36779192, 2023). "We observed relatively lower mRNA expression of inflammatory cytokines (IFN-γ, TNF-α, IL-4, IL-6, IL-17A and IL-33) in BA.5 infection as compared to ancestral Wuhan-Hu-1 infection." (PMID 37704701, 2023). "As was already observed after infection with S. mansoni, establishment of IL-4-producing Th2 T cells was only detected in spleens of N. brasiliensis-infected mice but not in their popliteal and inguinal lymph nodes." (PMID 36753434, 2023). "Serum levels of IgA and cytokines (IFN-γ, IL-4 and IL-6) were significantly elevated in infected unprotected group II when compared to healthy control group I on days 3, 7 and 14 after infection." (PMID 37943403, 2023). "The anti-inflammatory cytokine IL-4 showed increased expression level at the beginning and at the end of the infection period compared to the middle; however, this variation was significant only in the Lm+Bs and Ec inoculums (P<0.0001)." (PMID 36779192, 2023).